NGF (nerve growth factor)
Diseases named in the same sentence as NGF in open-access papers (continued):
Sharing a sentence is not in itself a finding about the gene and the disease.
glioma (continued). "We studied the effects of LL-37, PG-1, NGF, and TMZ on the clonogenicity of human glioma U251 cells over 1–7 days." (PMID 35956937, 2022). "Thus, LL-37 and NGF inhibit migration and clonogenicity of U251 glioma cells, which may indicate that these compounds have anti-mitogenic and anti-migration effects on human glioma cells." (PMID 35956937, 2022). "Probably, the inhibitory effects of NGF, LL-37, PG-1 on basal OCR on U251 glioma cells in our experiments can relation to the suppression of PAM16 overexpression or its protein." (PMID 35956937, 2022). "Recent studies have shown that nerve growth factor (NGF), neurotrophins (NTs), synaptic adhesion molecule neuroligin, and brain-derived neurotrophic factor (BDNF) promote the initiation, progression, and invasion of gliomas." (PMID 37788099, 2023). "Anti-mitogenic and anti-migration activities of NGF, LL-37, and TMZ maybe are relation to their capacity to reduce the basal OCR, ATP-synthetase, and maximal respiration of mitochondria in human glioma U251 cells." (PMID 35956937, 2022). "NGF (IC50 0.0148 and 0.0025 μM) showed the greatest antitumor efficacy in C6 glioma cell cultures." (PMID 35056889, 2022). "Anticancer activities of NGF, and LL-37, PG-1 maybe is relation to their capacity to reduce the basal OCR, ATP-synthetase, maximal respiration of mitochondria in human glioma U251 cells." (PMID 35956937, 2022). "LL-37, NGF, and TMZ inhibit migration and clonogenicity of U251 glioma cells, which may indicate that these compounds have anti-mitogenic and anti-migration effects on human glioma cells." (PMID 35956937, 2022). "We previously found that CA induces nerve growth factor (NGF) in U373MG human astrocytoma cells, T98G human glioma cells, and normal human astrocytes in an Nrf2-dependent manner and that CA induces neurite outgrowth of PC12h cells through an Nrf2- and p62-dependent pathway." (PMID 30959808, 2019). "We hypothesized that the TP membrane could serve for sustained TMZ release against glioma and the NGFP membrane could stabilize and deliver NGF for neuron cell proliferation and differentiation." (PMID 27548322, 2016). "In the present study, we examined whether SMase/ceramide induced up-regulation of NGF/p75NTR is mediated by CAPE-induced apoptosis, and we clarified the relationship between SMase/ceramide, NGF/p75NTR, and the MAPK signaling pathway in C6 glioma cells." (PMID 24997497, 2014). "Thus the aim of the current study was to evaluate the effects of nerve growth factor (NGF), human cathelicidin LL-37, protegrin-1 (PG-1), and temozolomide (TMZ) on the human U251 glioma cells in terms of bioenergetic function of mitochondria, clonogenicity, and migration rate." (PMID 35956937, 2022).
Anxiety (44 papers, 2012 to 2026). Intense feelings of nervousness, tension, or panic often arise in response to interpersonal stresses. "Previous research has identified neurotrophic factors, such as brain-derived neurotrophic factor (BDNF) and nerve growth factor (NGF), as biomarkers associated with temperament traits like emotional instability and anxiety-proneness." (PMID 40308388, 2025). "miR-144-3p targets a number of genes including Pten, Spred1, EGFR, Nrf2, AQP1, NGF, Brg1 and Notch, which are implicated in the stress response, anxiety and mood stabilizer treatment." (PMID 34674715, 2021). "In contrast, fewer studies have focused on other NTs, with the notable exception of NGF, which has been found to be increased during circumstances that cause anxiety or anticipation of anxiety." (PMID 27199779, 2016). "There is now evidence that reduced neurotrophin signaling contributes to the pathophysiology of neurodegenerative diseases, whilst decreased hippocampal NGF levels contribute to neurodegeneration associated with depressive and anxiety-like behaviors in folate-deprived animals." (PMID 37509019, 2023). "This decreases brain-derived neurotrophic factor (BDNF) and nerve growth factor (NGF) production within the hippocampus and promotes the development of anxiety." (PMID 39851502, 2025). "In this study, we addressed this question by using brain-specific Ngf conditional knockout (cKO) mice to reveal the importance of NGF in anxiety and spatial memory." (PMID 33723225, 2021). "Together, these data indicate that NGF plays a role in mediating anxiety and spatial learning/memory." (PMID 33723225, 2021). "In this study, we set out to investigate the roles of hippocampal NGF and the cholinergic system on anxiety, learning, and memory." (PMID 33723225, 2021). "Animal and human studies report reduced body weight, increased anxiety, and mood changes after NGF administration." (PMID 31506580, 2019). "Arousal or anxiety states are often accompanied by increases in NGF levels, which possibly reflect a central neuroprotective homeostatic mechanism with the potential to activate neuroendocrine and immune elements at the periphery." (PMID 25926799, 2015). "Unlike these mouse mutants, TrkAC-KI mice survived until adulthood and behaved normally in general locomotion and anxiety tests, thus for the first time allowing behavioral analysis of mice with genetically altered NGF/TrkA signaling." (PMID 24516396, 2014). "The key role of NGF in anxiety conditions is also suggested by findings demonstrating that alcohol or heroin withdrawal in human is also associated to changes in blood NGF levels." (PMID 22474604, 2012). "Also, uniquely associated with the anxiety/tension special factor was BDNF (brain-derived neurotrophic factor), which encodes a member of the nerve growth factor of proteins." (PMID 30867560, 2020). "Another NT that appears important in anxiety regulation is nerve growth factor (NGF)." (PMID 23785661, 2013). "A correlation between changes in NGF levels and anxiety-like behaviors has been observed in humans." (PMID 22474604, 2012). "Additionally, NGF affects anxiety behavior and conditioned fear in mice." (PMID 39595393, 2024). "Alternatively NGF may be acting outside the hippocampus to modulate anxiety." (PMID 33723225, 2021). "Further experiments using alternative Pdpn-down-regulation approaches like CRISPR-Cas9-based targeted Pdpn gene deletion could additionally contribute to the verification of the here proposed in vivo role of Pdpn in neurogenesis, NGF-mediated neuroprotection and anxiety-related behaviors." (PMID 32009902, 2019). "Notably, HSP resulted in a significant attenuation of anxiety- and depression-associated behaviors, a reduction in pro-inflammatory cytokine levels (TNF-α, IFN-γ, IL-1β, IL-2, IL-6), and an augmentation of neurotrophic factors (NT-3, BDNF, NGF) within the striatum." (PMID 41346684, 2025).
Anxiety (continued). "Changes in NGF and BDNF levels in serum have been detected in patients with neurodegenerative and psychiatric diseases, anxiety, mood disorders, and stress but the importance of distinguishing mature and precursor NTs has been pointed out only recently." (PMID 37175781, 2023). "Chronic administration of HBK-15 (1.25 mg/kg) and fluoxetine (10 mg/kg) protected corticosterone-treated mice from anhedonic-, depressive-, and anxiety-like behaviors, as well as decreases in BDNF and NGF levels in the hippocampus." (PMID 28550529, 2018). "Chronic treatment with the studied compound protected corticosterone-treated mice from anhedonic-, depressive-, and anxiety-like behaviors, as well as deceased BDNF and NGF levels in the hippocampus." (PMID 28550529, 2018). "Chronic treatment with the studied compound protected corticosterone-treated mice from anhedonic-, depressive-, and anxiety-like behaviors, as well as decreases in BDNF and NGF levels in the hippocampus." (PMID 28550529, 2018). "Further, two proteins, NGF and BDNF, which are involved in learning and memory performances, ageing-related disorders and anxiety-like behavior, were also analyzed in brain and adrenal gland." (PMID 22808101, 2012). "Therefore, our results demonstrated that linalool rescued the BDNF and NGF expression in MPP+-induced neurotoxicity in SH-SY5Y cells and improved depressive- and anxiety-like behaviors in MPTP-induced PD." (PMID 38473763, 2024). "Both in models and humans, stress, fear and anxiety are associated with enhanced rather than lowered serum levels of BDNF and NGF." (PMID 28068360, 2017). "Furthermore, we found that the effect of NGF on spatial memory, but not anxiety, requires the cholinergic projection to the hippocampus." (PMID 33723225, 2021). "Furthermore, NGF treatment did not affect the anxiety levels." (PMID 35928573, 2022). "In this study besides BDNF, we did not investigated the other members of the neurotrophin family which also includes Nerve Growth Factor (NGF), Neurotrophin-3 (NT-3) and Neurotrophin-4/5 (NT-4/5) because the available data indicate that they are not useful as biomarkers of anxiety." (PMID 26539329, 2015).
Cerebral ischemia (43 papers, 2006 to 2025). Restriction of arterial blood supply to the brain associated with insufficient oxygenation to support the metabolic requirements of the tissue. "Cerebral ischemia-reperfusion-induced lung injury was associated with increased expression of proNGF and p75NTR, as well as decreased NGF expression in lung tissue." (PMID 39549390, 2024). "Taken together, these findings suggest that functional recovery in cerebral ischemia is associated with not only BDNF or NGF, but it can also be mediated by NT-4 and other tyrosine kinase receptors." (PMID 23526925, 2013). "NGF is involved in the process of autophagy; however, the underlying mechanisms of proNGF/NGF on autophagy in cerebral ischemia-reperfusion (CIR) remain unclear." (PMID 35391929, 2022). "We reported that SMES demonstrates a safe and efficient ability to open the BBB during the cerebral ischemia repair phase, facilitating the delivery of NGF to the brain by the p65-VEGFA-TJs pathway." (PMID 38995444, 2025). "Acute cerebral ischemia is characterized by the decrease of endogenous expression of NGF, demonstrating the need to deliver exogenous NGF to the infarcted cortex to aid in recovery." (PMID 38505610, 2024). "The emergence of the Nerve Growth Factor (NGF) has promoted the development of neuroprotective therapy; however, it has little effect on cerebral ischemia because of its poor Blood-Brain Barrier (BBB) permeability." (PMID 39033586, 2024). "Modulating the NGF signaling pathway holds promise for mitigating cerebral ischemia-induced lung injury in elderly individuals, offering preliminary insights for the development of targeted therapeutic interventions." (PMID 39549390, 2024). "Rutin also attenuates neuronal loss in cerebral ischemia/reperfusion injury rats through estrogen receptor-mediated BDNF-TrκB and NGF-TrκA signaling pathways." (PMID 39877393, 2024). "Neurotrophins such as BDNF, NGF and NT-4 have been demonstrated to promote neurogenesis after cerebral ischemia." (PMID 38234630, 2024). "Rutin mitigates cerebral ischemia injury by activating estrogen receptor-mediated BDNF-TrkB/NGF-TrkA signaling, and chlorogenic acid mitigates ischemic injury by increasing the level of NGF in brain tissue." (PMID 35833035, 2022). "In recent years, neurotrophic factors such as nerve growth factor, brain-derived neurotrophic factor, and neurotrophin have been used to treat neurodegenerative diseases, including cerebral ischemia." (PMID 34773698, 2022). "NGF reduces inflammation by reshaping microglial polarization and promoting cell survival after cerebral ischemia." (PMID 36076942, 2022). "The delivery of NGF mRNA and protein via exosomes facilitates the recovery from brain damage by cerebral ischemia." (PMID 36076942, 2022). "Many neurotrophic factors, including BDNF, NGF, and NT-4 have been demonstrated to protect neural stem cells (NSCs) and to promote neurogenesis after cerebral ischemia." (PMID 34025400, 2021). "In the CNS, they are involved in neuroprotection against brain ischemia by increasing NGF and BDNF, important factors involved in the recovery of brain activities after an ischemic insult." (PMID 32344922, 2020). "NGF is also critical for neuronal survival, proliferation, and differentiation, and it has been reported that NGF is essential to improve neurological function after cerebral ischemia." (PMID 30581534, 2018). "In cerebral ischemia rat model and multiple sclerosis rats and mice models, iridoid glycosides also enhanced the levels of brain-derived neurotrophic factor and nerve growth factor." (PMID 29983732, 2018). "Intracerebroventricular or intracerebral administration of NGF will improve neurological recovery after cerebral ischemia or traumatic brain injury." (PMID 24671106, 2014).
Cerebral ischemia (continued). "On the other hand, one possible mechanism underlying brain ischemia-induced proliferation of neural progenitors is stimulation of tyrosine kinase-coupled receptors by induction of growth factors such as FGF, BDNF and NGF." (PMID 19943942, 2009). "This relationship suggests that the balance between NGF and proNGF, and their respective receptor interactions, may play a critical role in the development and severity of lung injury following cerebral ischemia-reperfusion." (PMID 39549390, 2024). "Rutin boosts the levels of estrogen receptor alpha and beta (ERα and ERβ), which modulate the growth, survival and metabolism of cells by regulating downstream targets and activating the BDNF-TrkB and NGF-TrkA signaling pathways, to mitigate cerebral ischemia injury." (PMID 35833035, 2022). "Whether it was short-term cerebral ischemia or prolonged ischemia, expression of NGF could be increased." (PMID 29423079, 2018). "Moreover, needling CV24, CV4, and CV3 has been shown to upregulate the expression of basic FGF, EGF, and NGF after cerebral ischemia reperfusion, activating nerve repair and proliferation of neuronal precursors." (PMID 30298094, 2018). "After cerebral ischemia, expression of endogenous NGF and its receptor were increased." (PMID 29423079, 2018). "Some studies have suggested increased NGF expression in cerebral ischemia." (PMID 29149884, 2017). "Additionally, NGF also protects neurons, alleviating brain ischemia-hypoxia and toxic damage." (PMID 40951886, 2025). "For example, the intraventricular administration of NGF, which increased the number of proliferating cells in vivo in the SVZ of aged mice, and intranasal administration of NGF to adult rats after cerebral ischemia may increase the survival of newly formed neurons and promote striatal neurogenesis." (PMID 34768919, 2021). "DWI and PWI could find the change of cerebral ischemia at the early stage, provide advantages for qualitative diagnosis of early-stage cerebral infarction and observation of efficacy in early treatment, initially showing that their great potential for NGF role on cerebral ischemia and mechanism." (PMID 29423079, 2018). "Pre-clinical studies in rats showed that exercise could lead to increase in the production of BDNF and NGF in a cerebral ischemia model, and consequently potentiate the resistance of the animal against brain injury induction by cerebral ischemia (Ang, Wong, Moochhala, & Ng, 2003)." (PMID 28446953, 2017). "Expression of a neurotrophin family protein, pro-NGF, was also significantly reduced in IVH (−0.72, 0.72; p ≤ 0.02), asphyxia (−0.72, 0.4; p ≤ 0.03), and cerebral ischemia (−1.13, 0.23; p ≤ 0.003)." (PMID 40003962, 2025). "Ruyi Zhenbao pill aids neurological recovery following cerebral ischemia/reperfusion by stimulating neurogenesis and angiogenesis, primarily through the upregulation of BDNF, NGF, and VEGF." (PMID 40520194, 2025). "This study aims to investigate the expression levels of Nerve Growth Factor (NGF), the precursor form of NGF (proNGF), and p75 neurotrophin receptor (p75NTR) in lung injury induced by cerebral Ischemia-Reperfusion (I/R) in both young and elderly rats." (PMID 39549390, 2024). "Brain-derived neurotrophic factor (BDNF) and nerve growth factor (NGF) are members of the neurotrophic factor family, which are important regulators of neuroregeneration after cerebral ischemia." (PMID 39090706, 2024). "The PC12 cell line was utilized as the in vitro model of cerebral ischemia, and LDH release was detected in different reperfusion conditions to evaluate cell viability to examine the neurotrophic activity of NGF and proNGF on cells following OGD/R." (PMID 35391929, 2022). "Under experimental cerebral ischemia and exercise conditions, the expression profiles of NT4/trkB as well as NGF/trkA and BDNF/trkB are changed." (PMID 23526925, 2013).
Cerebral ischemia (continued). "Shi demonstrated that chrysin could play a neuroprotective role in cerebral ischemia–reperfusion injury by upregulating the expression of brain-derived neurotrophic factor (BDNF) and nerve growth factor (NGF)." (PMID 39202984, 2024). "Thus, it was postulated that NGF could affect the neurological function resulting from cerebral ischemia by modulating Akt/mTOR to mediate apoptotic and autophagic activities after CIR, in the form of mature NGF and proNGF." (PMID 35391929, 2022). "A very similar expression-changing pattern was observed for the NT-3 transcript, a member of the neurotrophin family like BDNF; however, the expression of NGF, another member of the neurotrophin family was not statistically affected by the cerebral ischemia or stem cell transplantation." (PMID 35879657, 2022). "At this stage, cerebral ischemia had not yet produced irreversible damage, ischemic neuronal cells had not yet died, and the application of NGF and other neuroprotective agents could effectively maintain their survival." (PMID 29423079, 2018). "In these in vitro model systems of cerebral ischemia, no comparison of VEGF and NGF activation kinetics was performed." (PMID 16737552, 2006).